RNU7-48P (RNA, U7 small nuclear 48 pseudogene)
Synonyms: U7.48
Gene: Small nuclear RNA gene on chromosome 6 (70,513,294 to 70,513,356, forward strand). Ensembl gene ENSG00000238386.
Homologues: Orthologues: chimpanzee U7 (97% identical), macaque U7 (76% identical). Paralogues in human: RNU7-25P (86% identical), RNU7-2P (86% identical), RNU7-88P (86% identical), U7 (86% identical), RNU7-129P (84% identical), RNU7-20P (84% identical), RNU7-24P (84% identical), RNU7-37P (84% identical), RNU7-43P (84% identical), RNU7-57P (84% identical), RNU7-62P (84% identical), RNU7-70P (84% identical), and 143 more.